CXCL10 (C-X-C motif chemokine ligand 10)
Diseases named in the same sentence as CXCL10 in open-access papers (continued):
Sharing a sentence is not in itself a finding about the gene and the disease.
tumor (continued). "Notably, the Cxcl10 gene revealed the most significant change in both tumour models." (PMID 39219056, 2025). "In addition, CXCL10 influences the composition of the immune system in metastatic niches by suppressing cytotoxic responses and promoting the polarization of M2 macrophages, which further facilitates tumor seeding." (PMID 40760734, 2025). "The chemokines CCL2 and CCL5 well known attractants of CTLs as well as CXCL9 and CXCL10 powerful chemoattractant of activated CTLs were all highly induced by mIL12 mRNA treatment in both models and likely laid the ground for trafficking and retention of these effectors deep within the tumor cores." (PMID 40560386, 2025). "Similarly, patients were independently stratified by the quantile expression of CXCL10 tumor mRNA." (PMID 41463176, 2025). "Furthermore, high levels of CXCL10, IL-9, and CCL4 were associated with significantly higher numbers of T cells, especially for CTL with direct contact to tumor cells, whereas for VEGF the opposite effect was observed in the tumor stroma." (PMID 40497965, 2025). "Consequently, this process reframes circulating CXCL10 as a powerful, non-invasive biomarker that not only reflects tumor growth activity but also indicates the active, ongoing reprogramming of the pre-metastatic lung microenvironment and the sustained formation of pulmonary metastases in OS." (PMID 41516196, 2025). "Moreover, they suggest the TLR3/TICAM-1 may contribute to previously reported CXCL10-mediated recruitment of CXCR3-positive lymphocytes to the tumor microenvironment." (PMID 40029556, 2025). "Notably, RT plus Y332D markedly enhanced the infiltration of CXCR3+ T, CXCR3+ CD8+ T, CXCR3+ CD4+ T, and CXCR3+ NK cells versus either monotherapies or vehicle, potentially due to the recruitment of CXCR3‐positive lymphocytes into the tumor by CXCL10 secreted by tumor cells, which is promoted by RT." (PMID 40470716, 2025). "Consequently, therapeutic strategies targeting CXCL10 must be used with caution, as their use in immune-active tumor types may inadvertently lead to immunosuppression and compromise treatment efficacy." (PMID 40760734, 2025). "The chemokines CCL2 and CCL5 well known attractants of CTLs as well as CXCL9 and CXCL10 powerful chemoattractants of activated CTLs were all highly induced by mIL12 mRNA treatment in both models and likely laid the ground for trafficking and retention of these effectors deep within the tumor cores." (PMID 40321762, 2025). "In addition, analysis using the TISIDB database to determine correlations with various chemokines showed that STX4 also had a positive correlation with CXCL9 and CXCL10, which contribute to a "hot" tumor microenvironment and can increase immunotherapy effectiveness." (PMID 38226288, 2024). "In addition, the recruitment of cDC1 within tumors has other benefits, including the production of chemokines CXCL9 and CXCL10 to recruit CXCR3 effector T cells for tumor infiltration, and a further enhancement of the antitumor activity of T cells and NKs by cytokine IL-12." (PMID 38339158, 2024). "Indeed, the link between CXCR3 ligands, including both CXCL9 and CXCL10 in promoting anti-tumour immunity is becoming increasingly recognised, with their expression correlating with improved patient responses and sensitisation to immune checkpoint blockade in pan-cancer studies." (PMID 39165364, 2024). "Interestingly, increased expression of CCL19, CXCL9 and CXCL10 is associated with recruitment of immature CD56bright NK cells with low perforin content in the tumor microenvironment (TME), which is thought to protect tumor cells from NK cells." (PMID 40809150, 2024). "Moreover, activators of FAO, like bezafibrate, could potentiate anti-PD-1 therapy by inducing the expression of CXCL9 and CXCL10 from tumor cells and CXCR3 on intra-tumor effector T cells." (PMID 39119332, 2024). "Therefore, we investigated whether CXCL10 affects the anti-tumor effects of CD8+ T by regulating their glycolytic metabolism." (PMID 39346534, 2024).
tumor (continued). "The results revealed that αPD-L1scFv-hFc immunotherapy stimulated and activated T lymphocytes in CT26-derived BALB/c immunotherapy-sensitive model that may be the “hot tumor” characteristic with higher T cell population and tumor-intrinsic IFNs and CXCL10 expression." (PMID 38953994, 2024). "Therefore, we proposed and investigated whether LL/2 presented “cold tumor” characteristics, and CT26 presented “hot tumor” characteristics with differential IFNα and CXCL10 levels to determine the immunotherapeutic efficacy in this study." (PMID 38953994, 2024). "In our cohort, samples containing more CD8+ T cells, ≥ 10 cells per mm2, in the tumor parenchyma contained more CXCL9+ and CXCL10+ tumor cells, indicating that tumor cell expression of these key chemokines may also drive tumor parenchymal infiltration of CD8+ T cells." (PMID 38822345, 2024). "Therefore, we investigated the effect of CXCL10 on B16F10 tumor growth in vitro using an on-top assay involving a basement membrane culture of cells on top of a thin laminin-rich extracellular matrix gel to mimic the complex three-dimensional (3D) arrangement of tumors in vivo." (PMID 39268223, 2024). "Importantly, a trend for increased mRNA expression of CX3CL1 and CXCL10 in tumor cells was also observed upon dabrafenib treatment in vivo, suggesting that such a recruitment could take place in vivo." (PMID 38630384, 2024). "This may also explain why peripheral (systemic) administration of CXCL9-Fc or CXCL10-Fc limits tumor growth even though systemic administration of these agents would be expected to compromise the chemokine gradients that allow the endogenous CXCR3 ligands to attract T cells into the tumors." (PMID 39474427, 2024). "Therefore, while CXCL10 and Flt3L play vital roles in recruiting immune cells to the tumor microenvironment, they might require additional cytokines or signals to induce full immune activation." (PMID 38425844, 2024). "In addition to tumor-intrinsic CXCL10 expression, it is noteworthy that tumor-intrinsic IFNα may also contribute to M1 polarization, leading to M1 macrophage-mediated CXCL10 overexpression." (PMID 38953994, 2024). "The related mechanisms may involve an inhibitory effect on the IL-6/LIF system, promoting the release of ligands of the CXCR3 receptor, chemokines CXCL9 and CXCL10 (IP-9), which chemoattract several types of immune cells that infiltrate a tumor and prevent its growth." (PMID 38891915, 2024). "Thus, we tested if OSU13 promotes CCL5 and CXCL10 secretion by tumor cells using ELISA." (PMID 38900577, 2024). "Interestingly, chemokines in AITD (e.g., CXCL10), may be involved in the occurrence of tumor-related inflammation." (PMID 38298184, 2023). "Interestingly, VJDT monotherapy induced expansion of an iNKT cluster classified by the expression of Cxcl10, Icos, Traj18, and Klra5, while combinational treatment, which yielded the lowest tumor volumes, showed an increased presence of both MAIT cells and Rorc-expressing DNTαβ cells." (PMID 37651197, 2023). "Also, the WNT pathway activation would cause decreased expression of CXCL9 and CXCL10, making CTLs not being able to recruit to the tumor region." (PMID 37546397, 2023). "Therefore, the CXCL10/CXCR3 axis was indispensable in RFA-triggered anti-tumor immunity." (PMID 36900218, 2023). "In light of these data, it is hypothesized that V937 infection increases the production of interferon-gamma and CXCL10 by immune cells in the tumor microenvironment, particularly macrophages, which promote the response to anti-PD1 by properly guiding activated lymphocytes to dendritic cells." (PMID 37569757, 2023). "Therefore, in the context of NAFLD, CXCL10 may play an anti-tumor role in TNBC, but more in-depth experimental research is still needed." (PMID 37109526, 2023). "Furthermore, in the BRCA1 subset, CXCL10-positive expression showed a worse prognosis, suggesting that the axis may serve as a potential target in these tumours." (PMID 36831687, 2023).
tumor (continued). "Therefore, the promotion or inhibition effect of CXCL10 on tumor immunity may depend on the balance between CXCR3+CD8+ cells and CXCR3+ Tregs." (PMID 36782176, 2023). "CXCL10-derived peptides do not only inhibit vessel formation and induce the involution of newly formed vessels; these deformed and abnormal vessels may decrease the ingestion of chemotherapeutic drugs in tumour lesions too." (PMID 37686338, 2023). "Additionally, in vivo blockade of CXCL10 with AMG487 could partially reverse the pro-tumor effect from MFAP5 overexpression in CAFs and synergize with anti-PD-L1 antibody to enhance the immunotherapeutic effect." (PMID 37156839, 2023). "Therefore, ablation might promote the recruitment of cytotoxic CD8+T cells to infiltrate tumor tissues by up-regulating TAM1 to secrete CXCL10." (PMID 36900218, 2023). "has shown that succinate produced by F. nucleatum could inhibit the cGAS-IFNβ pathway, leading to reduced levels of chemokines CCL5 and CXCL10 in the tumor, thereby limiting the migration of CD8+ T cells to TME and suppressing the anti-tumor response of CD8+ T cells." (PMID 38023192, 2023). "Thus, DPP4 loss in RCC secretome may lead to the increased availability of CXCL10 for MSCs stimulating their migration toward tumor." (PMID 37563650, 2023). "Combined inhibition of EZH2 and DNMT1 augmented the expression of the inflammatory chemokines CXCL9 and CXCL10, which increased TILs and decreased tumor progression, thus improving the therapeutic efficacy of PD-L1 checkpoint blockade and adoptive T-cell transfusion in tumor-bearing mice." (PMID 37198402, 2023). "Interestingly, numerous reports confirmed that CXCL10 was a tumor marker in CRC." (PMID 36819776, 2023). "Of mechanistical relevance, advanced-stage CRC patients could also be characterized by the significantly decreased expression of the chemokine receptor CXCR3 on the surfaces of circulating CD8+ T cells, while the CXCR3 ligand CXCL10 turned out to be upregulated in the tumor tissue." (PMID 36428508, 2022). "Furthermore, in the ADT model, Tc17 cells reduced tumor growth as well as enhanced tumor infiltration of CXCL10+ MoDCs and CD8+ T cells, suggesting that the antitumor effect of Tc17 in vivo was not only from a direct cytotoxic killing effect of Tc17, but also from the recruitment of CD8 + T cells." (PMID 35459193, 2022). "To confirm the roles of CD8+ T cells and CXCL10 in the antitumor immune response following triple therapy administration, we depleted this population or cytokine in vivo and analyzed the effects on transplanted tumor growth and survival in the subcutaneous transplanted tumor model." (PMID 35121645, 2022). "Furthermore, RocA dramatically activated the cGAS (cyclic GMP-AMP synthase)-STING (stimulator of interferon genes) signaling pathway, and the inhibition/depletion of STING ablated the up-regulation of CCL5 and CXCL10, NK cell infiltration, and tumor regression induced by RocA." (PMID 35002511, 2022). "In addition, we further demonstrated that CC-01 induced CXCL10 gene expression in tumor, suggesting this treatment regimen may increasing unknown population in tumor-infiltrating lymphocyte (TIL), possibly natural killer (NK)-cells." (PMID 35058524, 2022). "This provides evidence that high expression of CXCL9 and CXCL10 in the intra-tumor environment of the body is significantly correlated with a high density of CD8+ T cells and that increased selective expression of CXCL9 and CXCL10 in Treg cell-depleted tumors may serve as a potential immunotherapy." (PMID 36479091, 2022). "Thus, inhibiting this pathway with trametinib allows chemotherapy (cisplatin/pemetrexed) to increase the CXCL10 expression and production by cancer cells, the recruitment of CD8 T cells within the tumor and the control of the tumor growth when associated with the anti-PD-1 antibody." (PMID 36429101, 2022).
tumor (continued). "CXCL10 signaling may induce an immunosuppressive niche allowing cancer cells to be accepted in various metastatic organs as well as in the immunosuppressive tumor microenvironment." (PMID 36230645, 2022). "In vivo alterations of the tumor immune environment involved fewer protumorigenic tumor-associated macrophages (TAMs) and MDSCs due to the suppression of IL-4, IL-13, and CXCL1 expression, and elevated infiltration by antitumor CTLs and NK cells attracted by elevated CXCL9 and CXCL10 levels." (PMID 35499071, 2022). "Along with epigenetic silencing of tumor-suppressor genes, in different types of cancer cells, EZH2 upregulation is linked with the transcriptional repression of genes that confer immunogenicity (e.g., MHC I and II) and support the recruitment of effector T cells (e.g., CXCL9 and CXCL10)." (PMID 33922336, 2021). "Thus, stimulating the tumor to secrete higher levels of CXCL10 could be a successful way to enhance the efficacy of adoptive NK cell therapy." (PMID 34572949, 2021). "Given that CXCL10 expression by tumors is associated with effective anti-tumor immunity and CD8+ T-cell regulation, we did not expect to observe a negative correlation between circulating levels of CXCL10 and PFS in patients with stage I NSCLC treated with SBRT." (PMID 34944879, 2021). "Pathogenic microorganisms and tumor cells can be eliminated by M1 macrophages by acute proinflammatory response, immune activation reaction, and cytophagy through the release of proinflammatory factors, such as NO, IL-1β, IL-6, TNF-α, and chemokines such as CCL2, CCL3, CCL5, CXCL9, and CXCL10." (PMID 34506209, 2021). "IFNA, IFNB and CXCL10 transcript levels were decreased in TRAMP-C2 and DU145 cells transfected with cGAS siRNAs and cGAS-deficient A549, HeLa, and HCT116 cells demonstrating that sensing of cytosolic DNA by cGAS contributes to the constitutive expression of type I IFNs in tumor cells." (PMID 33790360, 2021). "On the other hand, we demonstrated that monocytes infiltrating HT-29 spheroids may also possess anti-tumoral activities, as the secretion of CXCL10 and CXCL11, only secreted in HT-29 spheroids, and increasing upon monocyte addition, has been associated with tumor-suppressive functions." (PMID 34451433, 2021). "Consequently, CXCL10 performs homing functions to chemoattract CD8+ lymphocytes into the tumor bed." (PMID 34094037, 2021). "Also, CXCL10 demonstrated tumor-inhibiting properties in vivo." (PMID 34206510, 2021). "Thus, we speculate that, during the progression of PAAD, the correlation between the expression of CXCL10 in tumor cells and the abundance of Tregs cells will be weakened." (PMID 33681290, 2021). "Our results demonstrated that the elevated levels of CCL5 and CXCL10 produced by the irradiated tumors might attract the vaccinated CD8+ T cells with a high expression of IFN-γ+CXCR3+ into the tumor, resulting in an increased ratio of CD8+ T cells/Tregs in the tumor milieu." (PMID 33469123, 2021). "Interestingly, Methylobacteriaceae was positively correlated with CXCL10 in both tumor and adjacent normal mucosa in our CRC patients, and it has been reported to be associated with prognostically favorable T-cell markers and most corresponding recruiting chemokines." (PMID 34539647, 2021). "The increased release of CXCL10 at the tumor site upon C-7-mediated NK cell activation may lead to further attraction of immune effector cells to the tumor microenvironment and might, thus, potentiate other immunotherapeutic interventions, e.g., through immune checkpoint blockade." (PMID 34771609, 2021). "Notably, CXCL10 expression needs continuous stimulatory signals from the tumor microenvironment." (PMID 34345201, 2021). "Moreover, we observed that the production of CCL4, CCL5, CXCL9 and CXCL10 chemokines was induced by the co-culture of murlentamab-opsonized SKOV3-R2+ tumor cells with both M0 and TAM-like MDMs, while the normal fucosylated form 3C23K-CHO did not demonstrate any effects." (PMID 33924378, 2021).
tumor (continued). "In this study we found that blocking the oncogenic Wnt pathway by hsBCL9CT-24 could upregulate chemokine CXCL10 and improve T-cell tumor infiltration in cancer models, which are consistent with a recent report that Wnt pathway activation is linked to primary resistance in immunotherapy." (PMID 34790117, 2021). "Furthermore, IFNγ, produced by activated CTLs and abundant in inflamed tumours, can induce CXCL9 and CXCL10 secretion in various intermediary cells, including tumour-infiltrating myeloid cells, which may enhance the role of CXCR3 in homing." (PMID 33046212, 2020). "Therefore, we investigated whether CXCL5, CXCL9, and CXCL10 expression was correlated with immune infiltration levels in GC using the Tumor Immune Estimation Resource (TIMER) database." (PMID 33323542, 2020). "Furthermore, as cytokines can assist tumor progression, targeting IL-4, IL-13, IL-10, TGF-β, and CXCL5 or enhancing IFN-γ and some chemokines (e.g., CCL2, CCL3, CXCL9, CXCL10) may inhibit tumor invasion and metastasis." (PMID 32346605, 2020). "The observed synergy in tumor rejection extended to different tumor models, was accompanied by increased numbers of activated T cells expressing high levels of Gzma, Gzmb, Perforin, Cxcr3, and increased intratumoural levels of Cxcl9 and Cxcl10 compared to wild-type mice." (PMID 32641748, 2020). "The treatment increased the expression of IFNγ and CXCL9/CXCL10 in the tumor, as well as increased serum IFNγ/TNFα and expression of tumor-infiltrating lymphocytes, which may indicate the effectiveness of durvalumab/olaparib combination therapy in inducing an immune response in the tumor." (PMID 33327450, 2020). "This may give rise to a possible tumor supporting function of CXCL10 in brain metastasis." (PMID 32547545, 2020). "Therefore, enhancing the level of CXCL10 in tumor cell or TME could promote a strong T cells anti-tumor immunity, inhibiting tumor cells progress and angiogenesis." (PMID 32483450, 2020). "By using an ex vivo ovarian cancer (OVCA) model derived from patient samples, enhanced levels of proinflammatory signals (IFNγ, CXCL10, TNFα and IL-2) associated with a concomitant activation of CD4 and CD8 TILs could be observed when tumor cells were infected with TILT-123." (PMID 33202717, 2020). "IL-25 promotes the progression of HCC through inducing alternative activation and CXCL10 secretion of macrophages in tumor microenvironment, and IL-25 secretion may partly result from hyperplastic epithelial tuft cells in colon, induced by gut microbiota dysbiosis." (PMID 31296243, 2019). "This study highlights how the loss of mature miRNAs in TAMs during tumor progression leads to increased classically activated TAMs, improved CD8 response, and decreased CD8 suppression, which was associated with higher expression of CXCL10, CD86, and CXCL9 in the tumors." (PMID 31710308, 2019). "Thus, CXCL10 could be part of a wave of myeloid-derived factors contributing to a sustained immune response to the tumor." (PMID 31277459, 2019). "Furthermore, CD8 expression was positively correlated with the secretion of CCL5 and CXCL10 in LUAD, indicating that local production of CCL5 and CXCL10 may attract CD8+ T lymphocytes to tumor sites." (PMID 31221150, 2019). "Since CXCL9 and CXCL10 constitute two major molecules for effector T cells infiltration, it is speculated that combination of elemene and gefitinib might have an additional effect on enhancing anti-tumor T cell response." (PMID 30555330, 2018). "In addition, CXCL10 is strongly induced by IFN-ɣ in CXCR3A over-expressing cells (TPC-1) suggesting that CXCR3A-CXCL10 enhanced signaling might induce tumor progression promoting signals in PTC." (PMID 29416784, 2018). "Besides, various molecules, e.g., CXCL10 (C-X-C motif chemokine ligand 10), and certain cells, e.g., endothelial progenitor cells, were found capable of promoting tumor recurrence after liver transplantation in studies using relevant animal models and clinical specimens." (PMID 29642405, 2018).